BCAR1 (BCAR1 scaffold protein, Cas family member)
Diseases named in the same sentence as BCAR1 in open-access papers (continued):
Sharing a sentence is not in itself a finding about the gene and the disease.
gastric cancer (3 papers, 2016 to 2025). A primary or metastatic malignant neoplasm involving the stomach. "Additionally, the phosphorylation of BCAR1 at Tyr 410 is specifically associated with FLOT1 induced gastric cancer invasion and migration." (PMID 37928269, 2023). "Previous studies have shown that FLOT1 promotes gastric cancer progression and metastasis by interacting with BCAR1, specifically regulating its phosphorylation and translocation." (PMID 40303305, 2025). "Overexpression of BCAR1 promotes gastric cancer cell proliferation, migration, invasion and tumor growth." (PMID 37928269, 2023). "All these results from rescue experiments suggested that BCAR1 mediate FLOT1 induced gastric cancer proliferation, migration and invasion through ERK signaling." (PMID 37928269, 2023). "Collectively, all the results above indicated that FLOT1 and BCAR1 were overexpressed in gastric cancer tissue and was closely correlated with poor prognosis in gastric cancer patients." (PMID 37928269, 2023). "Here, we find FLOT1 promotes gastric cancer cell progression and metastasis by interacting with BCAR1, through ERK signaling." (PMID 37928269, 2023). "While knockdown of BCAR1 inhibits the ability of cell proliferation, migration, invasion and tumor growth in gastric cancer." (PMID 37928269, 2023). "Based on these results, it appears that phosphorylation of BCAR1 Tyr410 site is very important in FLOT1 induced gastric cancer cell migration and invasion." (PMID 37928269, 2023). "Furthermore, FLOT1 and BCAR1 expression is closely related to gastric cancer patients' poor outcome." (PMID 37928269, 2023). "Then how was BCAR1 phosphorylated in gastric cancer cells in which FLOT1 was upregulated?" (PMID 37928269, 2023). "BCAR1 knockdown could block FLOT1 induced gastric cancer cell proliferation, migration and invasion." (PMID 37928269, 2023). "We also identified the oncogenic role of BCAR1 in gastric cancer in vitro and in vivo." (PMID 37928269, 2023). "Moreover, BCAR1 overexpression can partially restore FLOT1 knockdown induced gastric cancer cell proliferation, migration and invasion." (PMID 37928269, 2023). "In this study, we demonstrated that FLOT1 promotes gastric cancer cell proliferation, migration and invasion in vitro and in vivo through BCAR1/ERK signaling, and regulates BCAR1 phosphorylation and translocation, which may provide a novel therapeutic target for gastric cancer treatment." (PMID 37928269, 2023). "Thus, our findings confirm that BCAR1 mediates FLOT1 induced gastric cancer progression and metastasis through ERK signaling, which may provide a novel pathway for gastric cancer treatment." (PMID 37928269, 2023). "To determine the oncogenic role of FLOT1 and BCAR1 in gastric cancer patients, we analyzed the expression of FLOT1, BCAR1, p-ERK1/2 and Ki67 in 80 gastric cancer samples and the paired adjacent normal gastric mucosa using IHC staining." (PMID 37928269, 2023). "In this study, we find FLOT1 promotes gastric cancer cell proliferation, migration and invasion through FLOT1/BCAR1/ERK pathway." (PMID 37928269, 2023). "Taken together, our study indicates that, BCAR1 mediates FLOT1 induced gastric cancer progression and metastasis through ERK signaling, which may present a novel therapeutic approach for gastric cancer treatment." (PMID 37928269, 2023). "To investigate whether BCAR1 mediates FLOT1 induced gastric cancer cell proliferation, migration and invasion, we transfected FLOT1 OE and control plasmids into BCAR1 KD HGC-27 and the corresponding control cells." (PMID 37928269, 2023). "Re-expression of wildtype rather than mutant BCAR1 (Y410F) could partially restore FLOT1 knockdown induced gastric cancer cell migration and invasion, while the restore could be inhibited by ERK inhibitor." (PMID 37928269, 2023).
invasive breast carcinoma (3 papers, 2017 to 2021). A carcinoma that infiltrates the breast parenchyma. "BCAR1 expression was significantly higher (p < 0.001) in colon adenocarcinoma (CoAd) than in prostate adenocarcinoma and breast invasive carcinoma." (PMID 34830244, 2021). "BCAR1 expression was significantly higher in the CoAd TCGA data set than in the breast invasive carcinoma set." (PMID 34830244, 2021).
non-small cell lung carcinoma (3 papers, 2012 to 2024). A group of at least three distinct histological types of lung cancer, including non-small cell squamous cell carcinoma, adenocarcinoma, and large cell carcinoma. "Recently, our study suggested there is a clinical implication of BCAR1 in non-small-cell lung cancer (NSCLC)." (PMID 22558353, 2012). "Notably, a study in non-small cell lung cancer also identified p130Cas/BCAR1 as a YAP interaction partner, promoting YAP activation in response to FAK activation." (PMID 39126118, 2024).
pancreatic cancer (3 papers, 2020 to 2025). "In pancreatic cancer, epidermal growth factor receptor (EGFR) induced Src activation, followed by the phosphorylation of p130Cas/BCAR1." (PMID 32906721, 2020).
coronary artery disease (2 papers, 2019 to 2024). "It is noteworthy that rs2870463 G near CTRB1 and BCAR1 was found to be significantly associated with decreased birthweight and higher risk of coronary artery disease." (PMID 30858448, 2019).
migraine (2 papers, 2017 to 2022). "Three further loci showed suggestive evidence for shared association (conjunctional FDR < 0.1), one of these (locus 5 near BCAR1) was previously identified as a cross-phenotype locus between migraine and CAD." (PMID 28957430, 2017). "Notably, seven of these genes (EHMT2, SLC44A4, PLEKHA1, CFDP1, TMEM170A, CHST6, and BCAR1) were genome-wide significant for all three traits (migraine, headache, and T2D)." (PMID 36292730, 2022). "Cross-trait gene-based overlap analysis identified 33 genes significantly associated (Pgene-based < 3.85 × 10−6) with migraine and T2D, and 11 genes associated with headache and T2D, with 7 genes (EHMT2, SLC44A4, PLEKHA1, CFDP1, TMEM170A, CHST6, and BCAR1) common between them." (PMID 36292730, 2022).
neuroblastoma (2 papers, 2023). Neuroblastoma (NB) is the most common solid, extracranial childhood tumor. "Among these, selective essentiality for GATA3 was only observed for high-NE-score neuroblastoma cell lines but not SCLC cell lines, whereas BCAR1 appears to be a shared vulnerability for low-NE-score cell lines in both neuroblastoma and SCLC." (PMID 37255415, 2023).
osteoporosis (2 papers, 2019 to 2024). A condition of reduced bone mass, with decreased cortical thickness and a decrease in the number and size of the trabeculae of cancellous bone (but normal chemical composition), resulting in increased fracture incidence. "Considering the role of p130Cas/BCAR1 at the cellular level this protein can be related to bone metabolism and diseases (osteoporosis, rheumatoid arthritis, bone invasion in the setting of cancer metastasis), cancer, immune system, and cardiovascular diseases (CVDs)." (PMID 39036012, 2024).
autoimmune disease (1 paper, 2020). A disorder resulting from loss of function or tissue destruction of an organ or multiple organs, arising from humoral or cellular immune responses of the individual to their own tissue constituents. "Three AMD-associated genes (BCAR1, CFDP1, and TMEM170A) residing within a locus on chromosome 16 (chr16:75233867-75516739), coincide with GWAS signals of six different trait groups, namely “organ function”, “cancer”, “neurological diseases”, “autoimmune diseases”, “metabolic traits”, and “AMD”." (PMID 32005911, 2020).
Azoospermia (1 paper, 2016). Absence of any measurable level of sperm,whereby spermatozoa cannot be observed even after centrifugation of the semen pellet. "We also identified new candidate genes, CREBBP and BCAR1, which may play a role in azoospermia." (PMID 27834916, 2016).
congenital heart disease (1 paper, 2022). A heart disease that is present at birth. "Our findings have implications for the mechanisms underlying the pathogenesis of congenital heart disease, and suggest that mice with conditional Bcar1 deletions may be useful models for dissecting mechanisms involved in the pathogenesis of human heart defects." (PMID 34270692, 2022).
cystadenoma (1 paper, 2015). A benign or borderline cystic epithelial neoplasm arising from the glandular epithelium. "Regrouping of the seven histotypes into three groups: cystadenoma, borderline cystadenoma and carcinoma, according to their outcomes, revealed that patients with carcinoma expressed significantly more CD41, BCAR1, LOX, FAK, VEGF and MVD compared with the borderline or cystadenoma groups." (PMID 25502723, 2015).
diabetes (1 paper, 2025). "ChIP-seq analysis in primary mouse islets confirmed CREB binding in active enhancers in Med14 S983 dependent diabetes-associated loci Bcar1/Ctrb1 and Peak1/Hmg20a." (PMID 40667025, 2025). "Furthermore, a number of genes in this set (Peak1, Astn2, Bcar1, Ctnnal1, Ppfibp2) is associated with significant diabetes-related risk loci." (PMID 40667025, 2025).
Headache (1 paper, 2022). Cephalgia, or pain sensed in various parts of the head, not confined to the area of distribution of any nerve. "Similarly, PLEKHA1 and BCAR1 overlapping headache and T2D were previously associated with headache." (PMID 36292730, 2022).
mastitis (1 paper, 2022). Inflammation of breast tissue during lactation or postpartum due to an obstructed duct or infection. "Polymorphisms in BCAR1 have previously been associated with SCC and mastitis resistance." (PMID 36613482, 2022).
pulmonary disease (1 paper, 2023). "The serum anti-estrogen resistance protein 1 (BCAR1 also known as p130-cas) is a molecular marker for pulmonary disease diagnosis and prognosis." (PMID 36608061, 2023).
cancer (85 papers, 2008 to 2025). A tumor composed of atypical neoplastic, often pleomorphic cells that invade other tissues. "In ERG-negative cancer, high levels of BCAR1 expression were significantly linked to presence of deletions of PTEN (p < 0.0001), CHD1 (5q21) (p < 0.0001) and MAP3K7 (6q15) (p < 0.0001), while these associations were lost in ERG-positive cancer." (PMID 29304771, 2018). "Furthermore, we found the expression level of FLOT1 was closely associated with phosphorylation of BCAR1 at Tyr 410, which plays crucial role in migration and chemoresistance of cancer therapy." (PMID 37928269, 2023). "In summary, the dynamic interactions of BCAR3 with BCAR1, HEF1, and various GTPases provide a complex regulatory network that is essential for normal cell cycle progression and potentially implicated in cancer when dysregulated." (PMID 38730626, 2024). "Although previous research well demonstrated the role of p130Cas/BCAR1 in different diseases especially cancers, a precise review study on the various effects of p130Cas/BCAR1 on cardiovascular diseases is missing." (PMID 39036012, 2024). "The P130cas adaptor protein, also known as BCAR1, is one of the Src substrates co-localizes with paxillin in FAs and is involved in cell migration, survival, transformation, invasion, and cancer." (PMID 36088346, 2022). "Other signaling proteins involved in transcriptional control include basic transcription factor 3 (BTF3) and breast cancer anti-estrogen resistance 1 (BCAR1) protein, which are downregulated upon Gal4 expression." (PMID 35742860, 2022). "Deregulation of p130Cas/BCAR1 adaptor protein has been extensively demonstrated in a variety of human cancers in which overexpression of p130Cas/BCAR1 correlates with increased malignancy." (PMID 34708040, 2021). "Among the top 50 DEGs, the cancer stem cell marker aldehyde dehydrogenase 2 (ALDH2), associated with drug efflux/resistance, was down-regulated after BCAR1 knockdown." (PMID 34830244, 2021). "High BCAR1 staining was associated with advanced tumor stage (p = 0.008), high Gleason score (p < 0.0001) and low preoperative PSA level (p < 0.0001) when all cancers were jointly analyzed." (PMID 29304771, 2018). "To better understand the prognostic power of BCAR1, we performed further subset analysis in cancers with identical classical and quantitative Gleason score in all patients and the ERG negative subset." (PMID 29304771, 2018). "Increased BCAR1 expression correlates with increased invasive potential of cancer cells, and silencing of BCAR1 or SHC3/4 results in decreased migratory ability." (PMID 30086712, 2018). "High BCAR1 staining was associated with PTEN deletion (p < 0.0001) and marginally associated with deletions of CHD1 (5q21) (p = 0.0084) when all cancers were jointly analyzed." (PMID 29304771, 2018). "BCAR1 staining was barely detectable in normal prostate glands but seen in 77.6% of 9472 interpretable cancers, including strong expression in 38.5%, moderate in 23.2% and weak in 15.9% of cases." (PMID 29304771, 2018). "For example, moderate or strong BCAR1 staining was observed in 79.3% of cancers with ERG rearrangement detected by FISH but found in only 57.3% of cancers without such rearrangements (p < 0.0001)." (PMID 29304771, 2018).
cancer (continued). "For example, in ERG-negative cancer, strong BCAR1 expression was found in 27.9% of pT2 cancers and increased by 9.3% to 37.2% in tumors ≥ pT3b, while the difference in ERG-positive cancer was only 1.7% between pT2 (51.9%) and ≥ pT3b (50.2%)." (PMID 29304771, 2018). "A tumor promoting role of BCAR1 overexpression fits well to the known function of BCAR1, which serves as a hub for several oncogenic pathways regulating processes like cell proliferation, growth, migration, and other cancer relevant cellular functions." (PMID 29304771, 2018). "Our study highlight that BCAR1 expression is associated with unfavorable tumor features and that the prognostic impact of BCAR1 is limited to ERG-negative cancers." (PMID 29304771, 2018). "BCAR1 has been correlated with controlling the spread and motility of cancer cells through regulating FA." (PMID 28217176, 2017). "Contrastingly, proteins that promote cell adhesion such as Paxillin (PXN), breast cancer anti-oestrogen resistance 1 (BCAR1) and Caveolin-1 (Cav-1) were upregulated." (PMID 28217176, 2017). "Breast cancer anti-estrogen resistance 1 (BCAR1), also entitled p130cas, was one of the CAS protein (Crk-associated substrate) family members." (PMID 22558353, 2012). "We used siRNA to knockdown expression of TNK2 and its proposed effector BCAR1 in order to analyse the effect of this knockdown on cancer cell behaviour in vitro." (PMID 18435854, 2008). "Gene expression analysis across all three cancer types subsequently found a common increase in the expression of five genes (BCAR1, COL1A1, IGSF3, RRAD, and TFPI2), which may further inform biomarker study for identifying CTCs." (PMID 36980717, 2023). "In addition, BCAR1 has been shown to enhance tumor proliferation, invasion, and metastasis in several cancers." (PMID 34055638, 2021). "Recently, we have identified interaction between PKN3 and adaptor protein p130Cas (Crk-associated substrate; BCAR1 in human) which promotes the pro-malignant growth of cancer cells and could partly explain PKN3-mediated phenotype." (PMID 33092266, 2020). "Studies have also reported an abnormal activation of the p130Cas/BCAR1 signaling network in various cancers that may lead to the upregulation of regulatory pathways, which can promote cell transformation." (PMID 33042270, 2020). "However, subset analyses revealed that the prognostic impact of BCAR1 expression was limited to ERG-negative cancer." (PMID 29304771, 2018). "Importantly, BCAR1 degradation had been proved to lead to anoikis of cancer cells in vitro." (PMID 28423562, 2017).